TNF (tumor necrosis factor)
Diseases named in the same sentence as TNF in open-access papers (continued):
Sharing a sentence is not in itself a finding about the gene and the disease.
tumor (continued). "The tumor necrosis factor-α (TNF-α)-inducing protein (tipα) gene family, comprising Helicobacter pylori membrane protein 1 (hp-mp1) and tipα, has been identified as a tumor promoter, contributing to H. pylori carcinogenicity." (PMID 33804551, 2021). "Particularly in the presence of a stimulus such as TNF, chemotherapy or TLR ligand this results in the formation of a RIPK1: caspase-8 complex, caspase-8 activation and the induction of tumor cell death." (PMID 34572737, 2021). "Tumor-bearing mice treated with T-cells and BiTEDs showed significantly elevated levels of systemic IL-2, IFN-γ, TNF-α, and IL-10, seven days after treatment." (PMID 33936101, 2021). "Consistently, tumor-infiltrating immune cells of B16-bearing HSD-fed RAG1−/− mice showed a significant up-regulation in IFNγ and a marginal increase in TNFα levels in NK cells." (PMID 34516769, 2021). "Qing-Re-Huo-Xue (QRHX) formulae increases the expression of iNOS and decreases the expression of IL-6, TNF-α, and Arg-1 through the JAK2/STAT3 pathway, further reducing the numbers of TAMs and inhibiting tumor growth in lung cancer mouse model." (PMID 33748122, 2021). "Strong interactions exist between TNF-α and further mediators such as CCL2, whose expression by tumor cells and macrophages is directly stimulated by TNF-α, thus sustaining a tumor-promoting effect." (PMID 34064859, 2021). "The results revealed significant changes including the increased expression of tumorigenesis-related markers, such as CD133, Bmi-1, VEGF, MMP-3, IL-1β, IL-6, TNF-α, and MDR, as well as the apoptotic markers, Bax and Bcl-xL, in the REM134-driven tumor group." (PMID 34527741, 2021). "The production of TLR‐4‐dependent TNF, a major response to CpG‐ODN, was found to be impaired by the administration of antibiotic cocktails in tumor‐bearing mice." (PMID 34026439, 2021). "Here, we report an increased high-avidity of tumor antigen-specific CD8+ T cells in the spleen from KV-treated animals, alongside increased Granzyme B expression and elevated proliferation, TNF-α and IFN-γ secretion." (PMID 34885215, 2021). "MSCs can be activated within tumor microenvironments by the pro-inflammatory cytokines TNF-α, IFN-γ or IL-1β, which are secreted by macrophages and tumor cells." (PMID 33472580, 2021). "On the one hand, tumor-associated neutrophils (TANs) may contribute to local hypoxia via respiratory burst-dependent oxygen expenditure; on the other hand, HIF1 regulates neutrophil functions and may promote neutrophil expression of pro-tumor factors, such as TNF-alpha, VEGFA, and MMP9." (PMID 33810575, 2021). "The levels of TNF-alpha (p<0.0001), IL-6 (p = 0.027), IL1-beta (p<0.0001) and MCP-1 (p<0.0001) in the tumor microenvironment were positively correlated with OSCC volume." (PMID 33411841, 2021). "However, other TNF-α-related tumor-suppressive effects may counter the effects of TNF-α on CSC." (PMID 33986746, 2021). "In addition, differentially methylated genes between tumor and adjacent normal tissues were detected and shown to be involved in many important biological pathways such as pathways in cancer, transcriptional misregulation in cancer, TNF signaling pathway, and hippo signaling pathway." (PMID 34868913, 2021). "NK cells also secrete a myriad of cytokines and chemokines, including IFN-γ, TNFα, IL-13, CCL3, CCL4, and GM-CSF, and, therefore, can modulate anti-tumor response by influencing trafficking other immune cells including cDC1s." (PMID 34367185, 2021). "Next, we found tumor-infiltrating CD38+ CD8+ T cells expressed higher level of CD103, IFN-γ, TNF-α and perforin than CD38− CD8+ T cells when were reactivated in vitro." (PMID 33934206, 2021). "Thus, lower level of IFN-γ/IL-2 producing CD4+ T cells of IN_in_r1-immunized mice may have indicated higher levels of CD4+ T cells producing IFN-γ/TNF-α, with the latter, or both events, contributing to a better protection of these mice against tumor challenge." (PMID 34199989, 2021).
tumor (continued). "Several adipokines, including tumor necrosis factor α (TNFα), interleukin (IL) 6, IL-8, and chemokine (C-C motif) ligand (CCL) 2 have been shown to play a role in tumor progression." (PMID 34283044, 2021). "Emodin significantly reduced tumor growth promoting necroptosis, as demonstrated by the increased levels of TNF-α (tumor necrosis factor α), RIP1, RIP3, and MLKL (mixed lineage kinase domain-like protein) observed in tumor tissues of the emodin-treated group." (PMID 34068184, 2021). "The up-regulated of CD276 expression can promote immune escaping of tumor cells, including inhibit the proliferation of T cells, reduce the secretion of IFN-γ, tumor necrosis factor-alpha (TNF-α), and other cytokines." (PMID 34178613, 2021). "The generation of oncolytic viruses that express TNF resulted in an enhanced anti-tumour effect when combined with LCL161, due to an increase in TNF-mediated bystander killing and collapse of tumour-vasculature." (PMID 31947615, 2020). "The TNF-mediated apoptotic pathway is a potent mechanism of inducing tumour cell death, and IAP antagonists rapidly sensitise tumour cells to killing by CTL-derived TNF." (PMID 31947615, 2020). "Thus, for some tumour contexts, fine-tuning TNF signalling might be beneficial." (PMID 32365592, 2020). "The fundamentals of cytokine gene therapy relies on the increase of cytokine levels with anti-tumor properties, including interleukin-2 (IL-2), IL-4, IL-6, IL-12, IL-24, interferon-alpha (IFN-α), IFN-γ, IFN-β or tumor necrosis factors (TNF) TNF-α and TNF-β." (PMID 32151052, 2020). "Fusion protein Cys–Asn–Gly–Arg–Cys–Gly–TNFα (NGR-TNFα), which targets the tumor vasculature delivering low amounts of TNFα, activates endothelial cells and allows CD8+ T lymphocytes infiltration." (PMID 32391269, 2020). "NK cells are known for its anti-viral and anti-tumor response, and secrete cytokines such as IFN-γ and TNF-α." (PMID 32765498, 2020). "Under NIR irradiation, tumor-bearing mice had higher activations of both CD4 and CD8 T cells in mouse spleens in treatment groups as well as an increase in IL-6, IL-12, and TNF-α in mouse serum." (PMID 33260534, 2020). "Since systemic administration of potent immunostimulatory factors, such as type I Interferons, tumor necrosis factor alpha (TNFα), or interleukin 12 (IL-12), may have considerable side effects, delivery by oAds provides an attractive option to focus cytokine activity on the target tumor." (PMID 33202717, 2020). "In tumor tissue, Lsp1-overexpressing CD4+ and CD8+ T cells also showed markedly reduced frequencies of TNF-α+ and/or IFN-γ+ cells compared with WT CD4+ and CD8+ T cells, respectively." (PMID 33020243, 2020). "Treg depletion was observed only in the tumor, where Teff can recognize cognate gp100 tumor antigen, and produced IFN-γ and TNF-α." (PMID 32005826, 2020). "Next, we demonstrated that TNF-α promotes protein expression of TAZ, a transcriptional coactivator necessary for self-renewal and tumor initiation in BCSCs27 in MCF7." (PMID 32019974, 2020). "Tumor cells expressing IDO have a higher chance of escaping the immune surveillance, and due to the presence of IFNγ and TNFα in the tumor microenvironment, they have a greater ability to migrate and invade." (PMID 32922383, 2020). "Th1 cells mainly secret cytokines such as IL-2, IL-12, TNF-α, and IFN-γ, which can enhance the cytotoxicity of immune cells to kill tumor cells and make the body's anticancer immune response stronger." (PMID 32351590, 2020). "mRNA levels of TNFα and COX-2 in irradiated adipose tissue adjacent to the tumor were decreased by DEX in tumor-bearing mice." (PMID 32325715, 2020). "TNF-α can also induce an increased expression of vascular endothelial growth factor (VEGF), the later of that can promote the proliferation of tumor cells and provide conditions for tumors metastasis." (PMID 32819324, 2020).
tumor (continued). "Efficient tumor-lytic activity after pharmacologic Vδ2 TCR-stimulation correlates with granzyme B and IFN-γ/TNF-α production in γδ T cells, parameters which we and others found to be enhanced when IL-2, IL-12, and IL-18 are added." (PMID 31947966, 2020). "TANs have been shown to induce genetic instability through the release of reactive oxygen species (ROS) and to produce tumor necrosis factor, IL-1, IL-6 and VEGF, which contribute to tumor proliferation and immune escape." (PMID 32711491, 2020). "TNF-mediated AICD was also observed upon activation of virus-specific CD8 T cells and tumor-infiltrating CD8 T lymphocytes." (PMID 32292509, 2020). "Amongst others, tumour necrosis factor-α (TNF-α) and IFN-γ are two major effector molecules in tumour destruction by CTL both targeting the tumour vasculature." (PMID 32184401, 2020). "Tumor tissue levels of transforming growth factor β1 (TGF-β1), thrombospondin 1 (TSP-1), and tumor necrosis factor α (TNF-α) were higher in 4T1 tumors than in 67NR tumors." (PMID 32156052, 2020). "In CLL, TNF-α is constitutively produced by the CLL B cells and carries an antiapoptotic role and sustains tumor proliferation." (PMID 33228048, 2020). "Tumor necrosis factor (TNF) and interferon‐γ (IFNγ) are essential to reject solid tumors and act both on tumor and stromal cells." (PMID 31916677, 2020). "Highly N-acetylated COS (NACOS) inhibits TNF-alpha-induced E-selectin expression in ECs via the JNK/NF-κB pathways, potentially attenuates tumor cell adhesion with ECs." (PMID 33262947, 2020). "CAR T-cells targeting EpCAM have been shown to significantly block tumor growth in xenografts and to secrete cytotoxic cytokines, including interferon-γ (IFN-γ) and tumor necrosis factor alpha (TNF-α) in vitro." (PMID 32849491, 2020). "NF-κB promotes the production of pro-inflammatory cytokines, such as members of the family of tumor necrosis factors, TNF-α and TNF-β, in tumor cells, which further promote cancer cell progression." (PMID 32962102, 2020). "While infection with the OV can lead to tumor destruction as previously discussed, the addition of IL2 and TNF-alpha increases the immunogenicity of the therapy." (PMID 33053757, 2020). "TNFα, MCP-1 and IL-10, which we previously reported to be enhanced in the tumour microenvironment following systemic IgE treatment in vivo, were secreted by monocytes alongside immune mediators CXCL-10, IL-4, IL-1β and IL-23." (PMID 33203088, 2020). "Based on such tumor-promoting aspects of TNFR1, efforts have been made to target TNF-α or TNFR1 in various malignancies with pharmaceuticals that include TNF-α inhibitors, TNFR1 monoclonal antibodies, and TNFR1-targeting nanomaterials." (PMID 32929358, 2020). "As with the tumor itself, TME also responds to RT by inducing the release of pro-inflammatory cytokines and other molecules, including PDGF, IL1β, TNFα, TGFβ, C-X-C motif chemokine 12 (CXCL12), MMPs, IL6, EGF, and VEGF." (PMID 32660072, 2020). "Consistent with the disruption of the BSCB, remarkably increased levels of IL-1β, TNF-α and MMP9 were observed in the tumor group of mice." (PMID 32796132, 2020). "Otherwise, it has been documented that in the model of epithelial carcinogenesis, cytokines TNF-α, was suggestively greater in PTX3-/- tumor homogenates compare to PTX3+/+17." (PMID 32194791, 2020). "Several serum factors such as TNF-α, IL-1β, IL-6, and a zinc-glycoprotein (ZAG), also called lipid-mobilizing factors secreted by tumor or host cells, have been shown to be involved in local as well as systemic AT lipolysis." (PMID 32120856, 2020). "Activated CD8+ T cells produce large amounts of proinflammatory cytokines such as tumor necrosis factor (TNF)-α and interferon (IFN)-γ and exhibit a profound tumor-directed cytotoxicity." (PMID 32194568, 2020). "In cancer, it has been shown that tumor cells through different mechanisms including VEGF and TNFα secretion are able to recruit ECFCs to form new vessels." (PMID 32546175, 2020).
tumor (continued). "Lymphokines TNF‐α and IFN‐γ were proven to be correlated with the cytotoxicity of CD8+ tumor‐infiltrating lymphocytes." (PMID 33034149, 2020). "These antigens can activate γδ T cells to secrete interferon γ (IFN-γ) and tumor necrosis factor α (TNF-α), or kill tumor cells through Fas/FasL and antibody-dependent cell-mediated cytotoxicity (ADCC)." (PMID 33664732, 2020). "NGR-human tumor necrosis factor (NGR-hTNF), a molecule already studied in clinical trials, was described to particularly bind to a tumor vessel specific CD13 isoform." (PMID 32084238, 2020). "We next investigated if tumor-secreted BMP7 regulates IL1A, IL1B, TNF, and CCL5 via MAPK14 in macrophages." (PMID 32973129, 2020). "During chronic inflammation, the cytokines tumor necrosis factor (TNF-α), interleukin 6 (IL-6), transforming growth factor β (TGF-β), and interleukin 10 (IL-10) have been shown to be involved in tumor induction, proliferation, and metastasis." (PMID 33023215, 2020). "We first analyzed the expression of TNF-α, the TNFR1 ligand and CCL-2, a chemokine involved in monocytes/macrophage recruitment to tumor sites." (PMID 33202705, 2020). "In a variety of tumor models, it was found that compared with NK cells around tumor, NK cells in tumor core express higher TIGIT, resulting in a significant decrease in anti-cancer factors such as IFN-γ and TNF produced by NK." (PMID 33344447, 2020). "In response to tumor ligands or intracellular pathogens, NK cells mainly produce Th1 type cytokines including IFN-g, TNF, and GMCSF which facilitate the activation of T cells, dendritic cells, macrophages, and neutrophils." (PMID 32793200, 2020). "Quantitative PCR and nanostring analysis of RNA isolated from these tumors revealed increased immune cell markers involved in mediating anti-tumor immunity, most notably CD4, CD8, IFN-γ, TNF-α, granzyme B, CD28, CD11c and CD11b are elevated in K46M mice." (PMID 32896273, 2020). "Specific immune response was manifested by coproduction of IFN-γ/IL-2/TNF-α characteristic to the effector CD8+ and CD4+ T cells, which can eliminate tumor cells." (PMID 32570805, 2020). "One interesting approach can be the co-activation of macrophages (MΦs) (retinoic acid), NK cells (IL-15, IL-22, and IL-23), cytotoxic T cells (CTLs) (IL-2, TNF-α, IFN-γ), and the acquisition and presentation of tumor antigens by dendritic cells." (PMID 33276556, 2020). "The results showed that dual blockade of PD1 and LAG3 synergistically enhanced anti-tumor immunity by inhibiting tumor growth and enhanced infiltration of CD4+ and CD8+ T cells, combined with the increased production of IFN-γ and TNF-α." (PMID 33488573, 2020). "IL-10 derived by TAM also supresses MHC class II expression on monocytes and down-regulates the production of IFN-γ and TNF-α in GBM, thus preventing anti-tumor activity." (PMID 32765498, 2020). "Tumor-derived TGF-β, together with other factors, such as VEGFA and TNFα, stimulates the release of chemoattractants, such as S100A8 and S100A9, that mediate the recruitment of immune cells in the pre-metastatic niche." (PMID 32397392, 2020). "Generally, cytotoxic T cell (CD8 + T cell) immune response is considered to have anti-tumor effects by IFN-γ, TNF-α and IL17." (PMID 32859214, 2020). "The paracrine factors such as TNF, WNT10A, PDGFA, and NRG1 were also elevated in tumor-infiltrating dendritic cells." (PMID 32434423, 2020). "Next, we assessed the ability of lamina propria T cells from unaffected tissue and tumor tissue to produce some of the cytokines important in tumor immunity (IFN-γ, IL-2, IL-17A, and TNF)." (PMID 32185408, 2020). "Tumor necrosis factor (TNF)-related apoptosis-inducing ligand (TRAIL) is a member of the tumor necrosis factor (TNF) superfamily and can induce apoptosis of tumor cells through activation of the TNF/CD95L axis and spare the majority of nonmalignant cells." (PMID 32587256, 2020).
tumor (continued). "It exhibits an anti-apoptotic effect through modulation of NF-κB, TNF, and AKT pathways and enhances tumour growth and angiogenesis through the VEGF pathway." (PMID 33053689, 2020). "Macrophages produce many factors that contribute to tumor growth, including VEGF, IL-1, IL-6, nuclear factor-kappa B (NF-κB), tumor necrosis factor-alpha (TNF-α) and macrophage colony-stimulating factor (M-CSF)." (PMID 32774171, 2020). "Treatment with CEA-TCB triggered secretion of pro-inflammatory cytokines (IFNγ, TNFα, IL-2) and several chemotactic molecules (CXCL9, CXCL10, CXCL11, CXCL13) indicating the generation of a highly inflamed tumor microenvironment." (PMID 33330050, 2020). "Exosomes isolated from B16 melanoma tumors in mice were shown to stimulate MDSCs to produce TNFα, MCP1, and IL6 in a MyD88-dependent manner, which promotes immunosuppression, tumor growth, and metastasis." (PMID 32547552, 2020). "In contrast, cytokine neutralization significantly reduced numbers and proliferation of CD8+ Teff and CD4+ Teff, as well as numbers of NK cells in the tumor, indicating the specific depleting action of IFN-γ and TNF-α on Tregs versus Teff subsets." (PMID 32005826, 2020). "There is a number of angiogenic mediators released by MCs in the tumor microenvironment including IL-8, NGF, TNF-α, TGF-β, and urokinase-type plasminogen activator (PA)." (PMID 31256327, 2020). "Daily administration of this strain before and after cancer induction significantly decreased tumor frequency, increased CD4+ and CD8+ T cells in tumor tissues, and decreased TNFα in the serum." (PMID 32523887, 2020). "The pro-inflammatory cytokines TNF-α and IL-1β are robustly involved in HCC tumor invasion, angiogenesis, and metastasis." (PMID 33718121, 2020). "In addition, intra-muscularly inoculated LLC-tumor bearing WT mice displayed increased protein degradation and loss of muscle mass, which was prevented in transgenic littermates overexpressing the soluble TNF receptor type 1 protein (sTNF-R1) to inhibit the actions of local or circulating TNF-α." (PMID 33329046, 2020). "The combination of ACA + anti-PD-1 also led to elevated frequencies of TNFα+ and perforin+ CD8 T cells within metastatic lungs, suggesting an improvement in systemic anti-tumor immunity." (PMID 33036247, 2020). "Upon engagement of tumor cells, CAR T cells secreted high amounts of pro-inflammatory cytokines like IFN-γ, IL23, and TNF-α." (PMID 32260097, 2020). "This study examined cytokine levels and found that the levels of inflammation-related cytokines, such as IL-6, IL-1β, and TNF-α, were decreased in FLP-treated MO mice in the tumour tissues compared to those of MO mice." (PMID 32308722, 2020). "In addition, it was also reported that basophils could release pro-inflammatory cytokines such as TNF-α, IL-6 and IL-1β, which augmented the inflammatory anti-tumor reaction, resulting in direct anti-neoplastic functions and inducing the apoptosis of tumor cells." (PMID 32037496, 2020). "TNF-α and ROS led to the overexpression of glucose transporters (GLUT-1 and GLUT-4), which were responsible for the nourishment of tumor cells." (PMID 33029095, 2020). "Conversely, the frequencies of TNF-α+ and/or IFN-γ+ cells in splenic CD4+ and CD8+ cells were significantly lower in Lsp1 Tg mice than in WT mice after tumor inoculation." (PMID 33020243, 2020). "In this study, we found that regulated by TNFα, Pim-2 proto-oncogene, serine/threonine kinase (PIM2) was highly expressed in HCC and correlated with poor prognosis (P = 0.007) as well as tumor recurrence (P = 0.014)." (PMID 32641749, 2020). "For example, chemokines (e.g., TNF-α, IL-6, and IL-1b) recruit immunosuppressive neutrophils and M2 macrophages to the TME, thereby inhibiting anti-tumor cell activity (e.g., TCD 8+ lymphocytes and NKTs)." (PMID 32208363, 2020).